COL1A1 (collagen type I alpha 1 chain)
Diseases named in the same sentence as COL1A1 in open-access papers (continued):
Sharing a sentence is not in itself a finding about the gene and the disease.
gout (2 papers, 2022). A condition characterized by painful swelling of the joints, which is caused by deposition of urate crystals. "A new study characterized plasma eccDNA in gouty arthritis and identified several eccDNA genes such as COL1A1 and EPB42, which were considered to be closely associated with hyperuricemia and gout." (PMID 36256570, 2022). "COL1A1 and EPB42, which potentially contribute to hyperuricemia and gout, were also revealed by gout eccDNAs." (PMID 35464862, 2022). "A total of 256 eccDNA-associated genes were detected as gout unique eccDNA genes, including COL1A1 and EPB42, which potentially contribute to hyperuricemia and gout, and a couple of genes involved in inflammation or immune response." (PMID 35464862, 2022).
Granuloma (2 papers, 2025). A compact, organized collection of mature mononuclear phagocytes, which may be but is not necessarily accompanied by accessory features such as necrosis. "Fibroblasts within Mtb granulomas displayed elevated expression of pro-inflammatory genes, recapitulating the broader inflammatory signature, and showed increased levels of tissue remodeling genes COL1A1 and FBLN1." (PMID 41586350, 2025).
human papillomavirus infection (2 papers, 2024). "The upregulated genes (n = 135) included ATM, COL1A1, FN1, ITGA6, and LAMB1, which were found to be enriched in pathways related to human papillomavirus infection and herpes simplex virus 1 infection." (PMID 40226717, 2024).
Hypodontia (2 papers, 2012 to 2021). The absence of five or less teeth from the normal series by a failure to develop. "In that study, treatment with BPs was not considered; instead, the very high prevalence of hypodontia and oligodontia prompted the group to investigate whether mutations in genes other than those earlier associated with OI (COL1A1, COL1A2, and CREB3L1) were responsible for the disturbances." (PMID 33743023, 2021).
kidney failure (2 papers, 2019 to 2022). An acute or chronic condition that is characterized by the inability of the kidneys to adequately filter the blood. "Surprisingly, analogous to observations in COL1A1, variants at the carboxyl end of their local collagenous region were associated with an increased risk of kidney failure." (PMID 35177655, 2022).
kidney inflammation (2 papers, 2022 to 2024). "Quantitative real time RT-PCR revealed a 11.5-fold increase of renal Col1A1 mRNA abundance in WT (1,054 ± 188%, p < 0.01) and a 11.7-fold increase in AnxA1-deficient mice (1,169 ± 113%, p < 0.01) at d10 after nephritis induction." (PMID 36311242, 2022). "Col1A1 mRNA was localized in fibroblasts in the periglomerular region of damaged glomeruli and the perivascular space of arcuate arteries in kidneys of mice at d10 after nephritis induction." (PMID 36311242, 2022). "In addition, Col1a1‐ or Emr1‐positive cells were present near the F2rl1‐positive tubular cells, suggesting a plausible role for PAR2 in kidney inflammation and fibrosis." (PMID 38687090, 2024).
leukaemia (2 papers, 2020 to 2024). "In the same way, we observed that leukaemia‐derived sEVs downregulated the expression of various genes (CXCL12, ANGPT1, COL1A1 and SCF) in BM‐MSCs, vital to maintaining normal haematopoiesis in BMM." (PMID 38499475, 2024).
leukoplakia (2 papers, 2024 to 2025). A white patch or plaque on a mucous membrane that cannot be characterized clinically or pathologically as any other disease. "Although our analysis compared OSCC to BC samples, 19 significant genes overlapped with Farah and Fox’s 47 differentially expressed genes (DEGs), including the upregulation of ODC1 and LCN2 and the downregulation of COL1A1, COL11A1, and STAC2 in dysplastic leukoplakia samples." (PMID 40650045, 2025).
liposarcoma (2 papers, 2025). A usually painless malignant tumor that arises from adipose tissue. "Fluorescence in situ hybridization (FISH) confirmed no PDGFB (22q13) translocation or COL1A1::PDGFB fusion, which are common in DFSP, and no MDM2 amplification, typically seen in liposarcomas." (PMID 40556675, 2025).
metastatic cancer (2 papers, 2023 to 2024). A carcinoma which has spread from the original site of growth to another anatomic site. "More specifically and importantly, COL1A1, COL1A2, and FAP were all highly expressed in metastatic cancer tissues, possibly indicated a higher chance of metastasis when abnormally expressed, which have not been reported before." (PMID 39034310, 2024). "Metastatic cancer-1 cells highly expressed mesenchymal markers (e.g., VIM, FN1, and COL1A1), typical of EMT, whereas metastatic cancer-2 cells highly expressed partial EMT (p-EMT) signature genes (e.g., LAMC2, PDPN, and INHBA), indicative of a p-EMT phenotype." (PMID 37853464, 2023).
mitral valve disease (2 papers, 2024). "Multiple regression analysis showed that mLASr was a predictor of atrial COL1A1 expression, compatible with previous studies showing that LASr is correlated with LA fibrosis detected by DE-CMR or histology in patients with mitral valve disease." (PMID 38976680, 2024).
multiple sclerosis (2 papers, 2013 to 2015). A progressive autoimmune disorder affecting the central nervous system resulting in demyelination. "COL1A1, COL3A1, COL5A1, and COL5A2 chains were induced significantly in active multiple sclerosis lesions and even more in inactive lesions." (PMID 26691002, 2015). "In contrast, the overexpression of the collagenous type II transmembrane protein (COL25A1) leads to AD-like pathology and different collagens, including COL1A1 and COL3A1, are induced in multiple sclerosis lesions." (PMID 23497022, 2013).
myocarditis (2 papers, 2019 to 2024). Myocarditis is a condition that is characterized by inflammation of the heart muscle (myocardium). "Next we determined expression of collagen genes in the heart during myocarditis and found that BPA exposure in drinking water significantly increased expression of collagen I (Col1a1) (p = 0.005) and collagen III (Col3a1) (p = 0.02) compared to control water." (PMID 31551929, 2019).
nodular fasciitis (2 papers, 2022 to 2024). A self-limiting, rapidly growing, non-encapsulated benign neoplasm that arises from the soft tissues. "Notably, we believed that FO may demonstrate more similar clinicopathologic and genetic manifestations with MO/FOPD and ST-ABC instead of nodular fasciitis for involving lower limbs most frequently and showing recurrent COL1A1::USP6 fusion." (PMID 36727055, 2022). "Our findings revealed that COL1A1 is the most common fusion partner in this entity, unlike primary aneurysmal bone cysts and nodular fasciitis." (PMID 36727055, 2022).
non-alcoholic fatty liver disease (2 papers, 2019 to 2020). "Intriguingly, our previous studies showed that EGCG treatment shared four common collagen-related genes Col1a1, Col1a2, Col3a1 and Col6a3 with atorvastatin treatment in non-alcoholic fatty liver diseases." (PMID 32290071, 2020).
Oligodontia (2 papers, 2020 to 2021). The absence of six or more teeth from the normal series by a failure to develop. "Seventy-five percent of the individuals presenting with oligodontia harbored mutations in COL1A1 and COL1A2 that were predicted to cause qualitatively changed protein." (PMID 32234057, 2020). "Except for the rare pathogenic variants in COL1A1, COL1A2, and CREB3L1, we were unable to identify any other pathogenic variant in a shared gene in the cohort that could explain the phenotype of oligodontia." (PMID 32234057, 2020). "Our findings suggest that mutations in COL1A1, COL1A2, and CREB3L1 may cause hypodontia and oligodontia in OI." (PMID 32234057, 2020).
osteogenesis imperfecta type 2 (2 papers, 2021 to 2024). Osteogenesis imperfecta type II is a lethal type of osteogenesis imperfecta (OI), a genetic disorder characterized by increased bone fragility, low bone mass and susceptibility to bone fractures. "The observed phenotype of Col1a1fapKO mice is analogous to the human type II Osteogenesis Imperfecta, which is lethal in the perinatal period due to critical genetic defects in COL1A1 or COL1A2 resulting in multiple rib and/or long bone fractures." (PMID 34893625, 2021).
osteopetrosis (2 papers, 2023). Osteopetrosis, also known as marble bone disease, is a descriptive term that refers to a group of rare, heritable disorders of the skeleton characterized by increased bone density on radiographs. "We utilized Atp6i deficient mice as an osteopetrosis disease model to study tooth root formation and found that Atp6i knockout mice exhibit disrupted tooth root formation with truncated HERS progression as well as marked decreases in odontoblast markers Dspp, Nfic, Nestin, Osx, and Col1a1." (PMID 37599332, 2023).
ovarian serous carcinoma (2 papers, 2014 to 2017). "Similarly, previous study also found that the expression of COL1A1 is increased in ovarian serous carcinoma compared normal tissues." (PMID 28775672, 2017).
ovarian tumor (2 papers, 2023 to 2024). "Next, the GEN2 database revealed the COL1A1 mRNA expression levels in ovarian tumors at various clinical stages." (PMID 39845977, 2024).
Papillary Thyroid Carcinoma (2 papers, 2022 to 2024). "Collagen genes are known to be associated with thyroid diseases, such as Col1a1, which is significantly upregulated in papillary thyroid carcinoma (PTC)." (PMID 39558975, 2024).
parasitic diseases (2 papers, 2021 to 2022). "COL1A1, COL1A2, and COL3A1 have been previously reported to be abnormally overexpressed in some tumors and parasitic diseases." (PMID 36034715, 2022).
Peritoneal Fibrosis (2 papers, 2023 to 2024). Disorder characterized by a wide range of structural changes in PERITONEUM, resulting from fibrogenic or inflammatory processes. "Under normal conditions, COL1A1 mRNA could be sponged by miR-1184 to prevent additional collagen deposition and peritoneal fibrosis." (PMID 38774747, 2024). "In TGF-β1-stimulated HPFBs, pro-fibrotic genes (COL1A1, COL1A2, ACTA2, CTGF, FN1, and TGFB1) exhibited higher expression than in controls, which are crucial targets of sildenafil and SB204741 against peritoneal fibrosis." (PMID 38322704, 2023).
psoriasis (2 papers, 2023 to 2025). An autoimmune condition characterized by red, well-delineated plaques with silvery scales that are usually on the extensor surfaces and scalp. "Similar to the IMQ-induced psoriasis model, MC903 application also led to suppression of Col1a1 expression in the skin, but AS injection failed to restore Col1a1 expression in MC903-treated skin." (PMID 36839900, 2023).
rheumatoid arthritis (2 papers, 2024). A chronic, systemic autoimmune disorder characterized by inflammation in the synovial membranes and articular surfaces. "In this study, we employed bioinformatics and machine learning techniques to identify seven key genes associated with rheumatoid arthritis (RA): AKR1B10, MMP13, FABP4, NCF1, SPP1, COL1A1, and RASGRP1." (PMID 39430588, 2024). "Although COL1A1 is well-studied in relation to these diseases, its role in rheumatoid arthritis (RA) has not been extensively explored." (PMID 39430588, 2024).
skin tumors (2 papers, 2021 to 2022). "Hence, we analyzed the expression of selected ECM components in skin tumors by qRT-PCR and found that the mRNA levels of α1 chains of collagen I (Col1a1) and III (Col3a1) and Tnc were significantly higher in Itga11+/+ papillomas than in Itga11−/− papillomas." (PMID 36003785, 2022).
soft tissue tumor (2 papers, 2023). "Imatinib was first approved by the FDA for the treatment of patients with soft tissue tumors bearing COL1A1–PDGFB fusion in 2006 and, according to a recent systematic review, was associated with objective responses in more than 60% of advanced cases." (PMID 36994196, 2023). "DFSP is a soft tissue tumor that was first named by Darier and Ferrand in 1924, and it carries a specific chromosomal translocation to form the COL1A1–PDGFB fusion gene." (PMID 37621777, 2023).
spindle cell neoplasm (2 papers, 2023 to 2025). A benign or malignant neoplasm characterized by the presence of neoplastic spindle cells. "Punch biopsy revealed a CD34-positive spindle cell neoplasm, and fluorescence in situ hybridization confirmed COL1A1 rearrangement, consistent with DFSP." (PMID 41466943, 2025).
synovitis (2 papers, 2017 to 2022). Inflammation of a synovial membrane. "Effects of synovitis ointment on bone cell fibrosis were detected through Masson staining, and the relative mRNA expression of PLOD2, COL1A1, TIMP1, and TGF-β was observed using the real-time quantitative (RT-PCR) method." (PMID 35815270, 2022). "While, the relative mRNA expression of PLOD2, COL1A1, TIMP1, and TGF-β was significantly decreased in the synovitis ointment group." (PMID 35815270, 2022). "To verify the effects of synovitis ointment on bone cells fibrosis, through RT-PCR assays, we examined the relative mRNA expression of PLOD2, COL1A1, TIMP1, and TGF-β under different treatment conditions." (PMID 35815270, 2022). "As expected, synovitis ointment decreased the levels of PLOD2, COL1A1, TIMP1, and TGF-β." (PMID 35815270, 2022). "The levels of PLOD2, COL1A1, TIMP1, and TGF-β were significantly higher in those lacking drug treatments than those treated with synovitis ointment (P < 0.05)." (PMID 35815270, 2022).
thyroid tumor (2 papers, 2020 to 2024). A benign or malignant neoplasm affecting the thyroid gland. "As we all know, COL1A1 has been found to be elevated in many cancers and affects various signal pathways, such as gastric, colorectal, breast and thyroid tumors 27-31." (PMID 38230216, 2024). "Overall, we showed the concurrent expression of α-SMA, LOX, and COL1A1 genes and proteins in BRAF-driven human thyroid tumors, where we also detected stroma associated local invasion." (PMID 31906302, 2020). "According to the model, CAFs are recruited in the stroma at the tumor invasive front where they synthesize and deposit collagen (COL1A1), which is in turn cross-linked by the enzyme LOX, produced by thyroid tumor cells." (PMID 31906302, 2020). "As validation of the proposed model, they investigated the expression of LOX and COL1A1 genes in human TC by using two public datasets and confirmed their upregulation in thyroid tumors as well as the association with BRAF mutation, but not RAS mutation." (PMID 31906302, 2020). "COL1A1 localized in tumor stroma and was closely correlated with α-SMA positive CAFs, whereas LOX was expressed by thyroid tumor cells." (PMID 31906302, 2020).
triple-negative breast carcinoma (2 papers, 2022 to 2025). An invasive breast carcinoma which is negative for expression of estrogen receptor (ER), progesterone receptor (PR), and human epidermal growth factor receptor 2 (HER2). "Collagen subunit proteins COL1A1, COL1A2, COL3A1, and COL11A1 have been related to triple-negative breast cancer: COL1A1 expression is elevated in TNBC tissues and is associated with increased tumor stiffness, promoting cancer progression and metastasis, making it an independent prognostic factor." (PMID 40867231, 2025).
uremia (2 papers, 2016 to 2022). A clinical syndrome associated with the retention of renal waste products or uremic toxins in the blood. "Meanwhile, by verifying the expression of these hub genes in the uremia-induced VC group, we found that Sost, Ibsp, Fn1, and Spp1 were highly expressed in calcified samples, while Col1a1 was lowly expressed." (PMID 35313524, 2022). "We constructed ROC curves of each hub gene separately and found that their area under ROC curves of Sost, Ibsp, Fn1, Col1a1, and Spp1 were all close to one in the uremia-induced VC group in GSE146638, with the normal group as control." (PMID 35313524, 2022). "Moreover, induction of uremia increased expression of fibrosis-related genes, most importantly Col1a1, Col3a1, and Fn1." (PMID 27992511, 2016).
viral infection (2 papers, 2022 to 2024). "Since PCLS could respond to fibrosis cocktails and induce Il6 and Col1a1, we concluded that viral infections, such as SARS-CoV-2, strongly suppress fibrosis." (PMID 36405683, 2022).
Achilles tendinitis (1 paper, 2020). "In the present study, we observed that nesfatin-1 increased osteogenic gene (COL1A1, RUNX2, and ALP) expression in TDSCs in vitro and promoted heterotopic bone formation in Achilles tendinitis in vivo." (PMID 33344440, 2020).
Acidosis (1 paper, 2022). Abnormal acid accumulation or depletion of base. "Additionally, the top seven nodes of the “Acidosis” network were present among the top ten nodes of “Acidosis and Bone metastasis”: COL1A1, COL3A1, COL4A1, COL4A2, ITGB3, THBS2, and ITGA11." (PMID 35159353, 2022).
acute endometritis (1 paper, 2024). An acute, usually bacterial infection affecting the endometrium. "Endometrial inflammation during LPS-induced acute endometritis significantly upregulated Col1a1 and Akt1 gene expression in mouse uterine tissues (p < 0.01), whereas leonurine was able to significantly reduce the inflammation-induced increase in Col1a1 and Akt1 gene expression." (PMID 39062636, 2024).
acute respiratory distress syndrome (1 paper, 2021). Progressive and life-threatening pulmonary distress in the absence of an underlying pulmonary condition, usually following major trauma or surgery. "PECAM1 was reported to be involved in lung repair and regeneration in acute respiratory distress syndrome whereas COL1A1 is correlated with hypoxia markers in NSCLC." (PMID 33511215, 2021).
adenomyosis (1 paper, 2022). The growth of endometrial tissue inside the muscular wall of the uterine corpus. "COL1A1 and COLIII protein immunoreactivity was significantly increased (P = 0.009 and P = 0.024) in the absence of significant changes in the corresponding mRNA in endometrium of women with adenomyosis." (PMID 35773139, 2022).
Adrenal insufficiency (1 paper, 2025). Insufficient production of steroid hormones (primarily cortisol) by the adrenal glands. "No other pathogenic variants were found in genes associated with skeletal dysplasias (e.g., FGFR3, COL1A1), adrenal insufficiency (e.g., NR0B1, STAR), or growth retardation (e.g., IGF1R)." (PMID 41218602, 2025).
alveolitis (1 paper, 2025). "Importantly, blocking the C5a/C5aR1 signaling either before or after the initiation of fibrosis led to significant reductions in lung tissue cell numbers, alveolitis scores, Ashcroft scores, collagen deposition, and the expression of fibrosis-related genes, including Acta2, Col1a1, Col3, and Fn1." (PMID 40867551, 2025).
ameloblastoma (1 paper, 2022). The most common odontogenic tumor, arising from the epithelial component of the embryonic tooth and usually affecting the molar-ramus region of the mandible or maxilla. "No specific research was found demonstrating the association between COL1A1 and ameloblastoma." (PMID 36160115, 2022). "According to the present results, COL1A1 was considerably upregulated in ameloblastoma tissues compared to the healthy controls with the criteria of FC = 6.73 and P value = 0.00098." (PMID 36160115, 2022). "Due to the upregulation of several ECM-related genes in ameloblastoma, it may be suggested that COL1A1 is involved in the tumorigenesis of the disease." (PMID 36160115, 2022).
anaplastic carcinomas (1 paper, 2025). "A single study included also a small set of PDC reported the expression of CAF-associated markers (collagen type 1 gene, COL1A1, and alpha smooth muscle actin gene, ACTA2) in such cases, similar to papillary and anaplastic carcinomas." (PMID 39849146, 2025).
anemia (1 paper, 2025). A reduction in the number of red blood cells, the amount of hemoglobin, and/or the volume of packed red blood cells. "Blocking CD47 or SIRPα promotes macrophage clearance of necHCs and reduces HSC activation (α-SMA, Col1a1); anti-SIRPα avoids anemia associated with CD47 blockade." (PMID 40630093, 2025).